NAMPT (nicotinamide phosphoribosyltransferase)
Diseases named in the same sentence as NAMPT in open-access papers (continued):
Sharing a sentence is not in itself a finding about the gene and the disease.
Salmonella Infections (1 paper, 2021). Infections with bacteria of the genus SALMONELLA. "Salmonella infection causes significant upregulation of the NAMPT gene in mice." (PMID 34461813, 2021).
skin cutaneous melanoma (1 paper, 2021). "Human melanoma tumor data from TCGA were analyzed for survival, degree of immune cell infiltration, and NAMPT expression level in tumor biopsies in the skin cutaneous melanoma (SKCM) collection." (PMID 33976173, 2021).
squamous cell cervical cancer (1 paper, 2020). "We carried out a multivariate Cox regression analysis and developed six ARG-related prognostic signature for the survival prediction of patients with squamous cell cervical cancer (Risk score = − 0.63*ATG3–0.42*BCL2 + 0.85*CD46–0.38*IFNG+ 0.23*NAMPT+ 0.82*TM9SF1)." (PMID 33160404, 2020). "Next, we carried out multivariate Cox regression analysis and identified 6 genes (ATG3, BCL2, CD46, IFNG, NAMPT, TM9SF1) that were independently associated with OS in squamous cell cervical cancer patients." (PMID 33160404, 2020). "After univariate and multivariate Cox regression assay of differentially expressed ARGs, 6 ARG (ATG3, BCL2, CD46, IFNG, NAMPT, TM9SF1) related prognostic signatures for squamous cell cervical cancer were constructed." (PMID 33160404, 2020).
tendinopathy (1 paper, 2023). "NAMPT was significantly increased in ADMSCyoung-EVs, and NAMPT regulation and subsequent NAD+ production in both tenocytes and macrophages protected against tendinopathy." (PMID 36604715, 2023).
thyroid nodule (1 paper, 2018). A small circumscribed mass in the THYROID GLAND that can be of neoplastic growth or non-neoplastic abnormality. "Taking into consideration the crucial role of NAMPT in regulation of cell proliferation, we would explain its overexpression in thyroid nodules." (PMID 29546048, 2018).
uterine cancer (1 paper, 2024). Primary or metastatic malignant neoplasm involving the uterine corpus and/or the cervix. "Analysis of TCGA database showed gene amplification of NAMPT and NMNAT2 at relatively high frequency in various types of cancer, including pancreatic, breast, ovarian, and uterine cancers." (PMID 38625917, 2024).
cancer (305 papers, 2010 to 2026). A tumor composed of atypical neoplastic, often pleomorphic cells that invade other tissues. "To better understand the high-risk role of NAMPT, we assessed its prognostic impact in other cancer types." (PMID 40280967, 2025). "An understanding of how these mechanisms interact with the biology of each given cancer cell type to predispose to the acquisition of NAMPT inhibitor resistance will be necessary to develop strategies to optimize the use of these agents moving forward." (PMID 40342733, 2025). "Visfatin, also known as nicotinamide phosphoribosyltransferase (NAMPT), plays a crucial role in metabolism and has been implicated in cancer progression." (PMID 40282553, 2025). "Numerous reports also highlighted an association between high NAMPT levels and poor clinical outcomes, including worse survival, for different types of cancer." (PMID 38396769, 2024). "A novel NAMPT inhibitor (A4276) selectively targets NAPRT-deficient EMT subtype cancer cells and alleviates chemotherapy-induced peripheral neuropathy." (PMID 38469234, 2024). "A novel NAMPT inhibitor that selectively targets NAPRT-deficient EMT-subtype cancer cells and provides relief from chemotherapy-induced peripheral neuropathy is currently being studied." (PMID 39766263, 2024). "This study aimed to identify a novel NAMPT inhibitor with enhanced selective cytotoxicity against NAPRT-deficient cancer cells as well as prominent efficacy in alleviating CIPN." (PMID 37771778, 2023). "Although crucial to normal systemic functionality, NAMPT has recently been associated with tumorigenesis, and its increased expression is associated with the pathogenesis or various cancers." (PMID 37583931, 2023). "The secreted form of NAMPT (eNAMPT, extracellular NAMPT) has been reported to reflect cytokine function and is associated with cancer and inflammatory disease incidence." (PMID 36830834, 2023). "Both intracellular (iNAMPT) and extracellular (eNAMPT) forms of NAMPT have pro-oncogenic and pro-inflammatory effects, and their increased expression is associated with a poor prognosis in cancer." (PMID 37175631, 2023). "Both in vitro and In vivo comparative analyses were conducted between A4276 and other NAMPT inhibitors to evaluate the NAPRT-negative cancer cell selectivity and the underlying distinct NAMPT inhibition mechanism of A4276." (PMID 37771778, 2023). "NAMPT has been detected in both plasma and tumors from cancer patients, suggesting the potential diagnostic significance of NAMPT in cancer." (PMID 35565188, 2022). "PAK4 forms a protein complex with NAMPT, which is crucial for mitochondrial function and has been implicated in cancer metabolism and stemness." (PMID 35241781, 2022). "The statistically significant association between the circulating NAMPT (visfatin) levels and the cancer risk has been discovered." (PMID 35565188, 2022). "Patients diagnosed with thyroid malignancy were discovered to have higher level of NAMPT expression, and the association of NAMPT level with cancer metastasis and advanced tumor stage was reported." (PMID 35565188, 2022). "Due to their dependency on the Nam salvage pathway for survival, NAPRT-deficient cancers are extremely sensitive to treatment with NAMPT inhibitors." (PMID 35890155, 2022). "Recent discoveries have demonstrated the indirect association and direct biological functions of NAMPT in modulating cancer metastasis, proliferation, angiogenesis, cancer stemness, and chemoresistance to anticancer drugs." (PMID 35565188, 2022). "In this review, we will first present a comprehensive explanation of NAMPT’s basic biological functions and its association with cancer, then we will talk about current clinical development status and observations." (PMID 36160449, 2022).
cancer (continued). "We integrated and summarized the current knowledge on this topic, focusing on NAMPT somatic mutations and evidence of NAMPT expression in different tumor types and on NAMPT-mediated biological functions in modulating cancer progression." (PMID 35565188, 2022). "For example, in most EMT subtypes of gastric tumors, the loss of NAPRT expression makes cancer cells more dependent on NAMPT to produce NAD+." (PMID 35906622, 2022). "High NAD+ and NAMPT expression have also been shown to be associated with the presence of a higher proportion of cancer-initiating/stem cells." (PMID 36497496, 2022). "On the basis of the current understanding of NAMPT regulatory mechanisms and developing evidence for NAMPT’s pathogenic functions in human cancer, the further study of NAMPT inhibitors is unquestionably significant for the treatment of cancer." (PMID 36160449, 2022). "In vitro studies have demonstrated that employing NAMPT inhibitors to treat cancer cells, particularly cancer cell lines with IDH1/2 mutations, is considerably effective." (PMID 36160449, 2022). "Generally, increased expression of these microRNAs was shown to suppress NAMPT expression and it was associated with reduced cancer cell viability, suggesting the potential use of these microRNAs as anti-cancer agents." (PMID 34068917, 2021). "Cancer cells and activated immune cells express high nicotinamide phosphoribosyltransferase (NAMPT) levels and are highly susceptible to NAMPT inhibitors (NAMPTi), as shown by activity of these agents in malignant disorder models." (PMID 34201149, 2021). "Nevertheless, elevated expression of QAPRT, the rate-limiting enzyme in the de novo NAD pathway, has been reportedly associated with resistance to NAMPT inhibitors, but also to chemotherapeutic agents in multiple types of cancer." (PMID 34068917, 2021). "NAMPT is overexpressed in many different types of tumors, and its expression appears to be associated with cancer progression." (PMID 32454935, 2020). "In several preclinical models, combinations of NAMPT and PARP-1 inhibitors have been shown to induce cancer cell death and tumor regression, revealing a synthetic lethal interaction between NAMPT and PARP-1 deficiencies." (PMID 32807821, 2020). "Studies in clinical CRC tumor samples revealed that high NAMPT expression was associated with the presence of a high proportion of cancer-initiating cells." (PMID 32010616, 2019). "Loss of NAPRT in cancer cells make cancer cells sensitive to NAMPT inhibitor FK866 and possibly also allow increasing the therapeutic efficiency of FK866 by coadministration of NA analog." (PMID 31448236, 2019). "Other cancer types with DNA repair deficiencies have been identified as selectively sensitive to NAMPT inhibitors." (PMID 32010616, 2019). "For example, IDH mutant cancers have been shown to have exquisite sensitivity to NAMPT inhibitors, as have tumors deficient in NAPRT." (PMID 32010616, 2019). "Continuous exposure of cancer cells to NAMPT inhibitors can result in acquired resistance to these drugs, often caused by mutations in NAMPT." (PMID 29662658, 2018). "In this study, we generated a cancer cell line that is cross-resistant to diverse NAMPT inhibitors, identifying the mutation responsible for resistance, and elucidated the molecular mechanisms of action." (PMID 29662658, 2018). "In the cancer-associated salvage pathway, nicotinamide phosphoribosyltransferase (NAMPT) is the rate-limiting step in the production of the NAD+ precursor molecule nicotinamide mononucleotide (NMN)." (PMID 30631752, 2018). "A more recent study has demonstrated that recurrent NAMPT-H191R mutations confer resistance to STF-31 treatment in cancer cell lines and that STF-31 also exerts an additional inhibitory effect against Nampt." (PMID 30631755, 2018). "Elevated expression of NAMPT has been implicated in MM and cancers of the prostate, brain, colon and rectum." (PMID 24690091, 2014).
cancer (continued). "We conducted meta-analysis of genome-wide expression data to identify NAMPT-influenced genes implicated in cancer pathobiology." (PMID 25146220, 2014). "This is consistent with other studies in many other types of cancer, in which NAMPT is overexpressed or mutated." (PMID 24279986, 2013). "PARG and NAMPT inhibitors could therefore represent therapeutic opportunities for cancers displaying PARP1 hyperactivity, including XRCC1-deficient cancers." (PMID 41459749, 2025). "Indeed, due to their dependency on the NAD+ salvage pathway, salvage-dependent cancers with NAPRT deficiency are sensitive to treatment with NAMPT inhibitors." (PMID 38116009, 2023). "The pro-cancer function is based on the increased expression of NAMPT, which is associated with the secretion of pro-proliferative cytokines, promoting the growth and development of cancer cells, stimulating angiogenesis, promoting metastasis or affecting genome stability." (PMID 37190027, 2023). "In conclusion, the results strongly suggest that A4276 is an NAMPT inhibitor that exhibits remarkable selectivity against NAPRT-deficient EMT-like cancer cell lines across various cancer types while effectively sparing NAPRT-positive cells, particularly, normal cells." (PMID 37771778, 2023). "Importantly, oxidative stress appears to be the main cause of cancer cell death after NAMPT inhibitor treatment." (PMID 36838885, 2023). "Furthermore, NAMPT expression is upregulated in most cancer cells and is associated with tumor progression." (PMID 36838885, 2023). "Moreover, in NAPRT- and NAMPT-dependent cancers where the related enzyme is deficient, an alternative route for producing NAD+ via NRK1 is activated." (PMID 37175631, 2023). "We hypothesized that A4276 has high selectivity for NAPRT-deficient cancer cells due to it inhibiting NAMPT enzymatic activity, as these cancer cells are likely dependent on NAMPT for NAD+ supply." (PMID 37771778, 2023). "NAMPT inhibitors have not only showed promise as a monotherapy, but they have also been proven in vitro and in vivo investigations to prolong the therapeutic decline caused by cancer resistance to other medication treatment modalities." (PMID 36160449, 2022). "NAMPT over-expression is a feature of several cancers, not only the BRAF-mutated ones." (PMID 35272691, 2022). "Cancer cells are more susceptible to NAMPT inhibitors compared to normal cells." (PMID 36233428, 2022). "In general, increased expression of these microRNAs can inhibit NAMPT expression and is associated with a decrease in cancer cell viability, suggesting that these microRNAs may have potential as anticancer drugs." (PMID 36160449, 2022). "Numerous cancers have been linked to the interaction between mTOR and NAMPT." (PMID 36160449, 2022). "Consequently, NAMPT inhibition has been shown to result in the loss of cancer stem cells through excess autophagy resulting in the disruption of the maintenance of cancer-cell stemness." (PMID 36497496, 2022). "Emerging evidence regarding NAMPT somatic mutations in cancer patients, NAMPT expressional signatures in normal tissues and cancers, and the prognostic significance of NAMPT in many cancer types has attracted attention, and NAMPT is considered a potential biomarker of cancer." (PMID 35565188, 2022). "A recent study reported overexpression of the NAPRT gene in a subset of common types of cancer such as breast, prostate, liver, pancreatic, ovarian, and head and neck cancers, where it promotes cancer cell metabolism and reduces the susceptibility to NAMPT inhibitors and DNA-damaging drugs." (PMID 33609766, 2021). "Taken together, the mechanism underlying cancer cell death in response to NAMPT inhibitors might be cancer type-specific and regulated in a dose and time-dependent manner." (PMID 34068917, 2021).
cancer (continued). "An additional, H2S-regulated bioenergetic pathways that may become upregulated in cancer cell include the nicotinamide phosphoribosyltransferase (Nampt) (which has been implicated in the cancer cells’ ability to recover from hypoxic or oxidative damage)." (PMID 33499368, 2021). "NAMPT inhibition in cancer has been associated with an increase of AMPK activity." (PMID 33384409, 2021). "Interestingly, we found that the TAM1 and TAM3 cells also show high expression levels of multiple oncogenes, such as DUSP1, IER2 and NAMPT, which have been implicated in cancer progression." (PMID 34805184, 2021). "Overexpression of NAMPT has been implicated in several cancers." (PMID 32111066, 2020). "Additionally, in several studies, NAMPT inhibition enhanced cancer cell susceptibility to oxidative stress through a reduction in antioxidative capacity via downregulation of antioxidant proteins." (PMID 32010616, 2019). "In one study, the loss of cancer stem cell pluripotency upon inhibition of NAMPT was the result of an excess of autophagy, a well-described consequence of NAMPT inhibition, which disrupted the maintenance of cancer cell stemness." (PMID 32010616, 2019). "Therefore, overall, these data indicate that LDHA plays a pivotal role in the metabolic rewiring that underlies cancer cells’ acquired resistance to NAMPT inhibition in our models." (PMID 29541451, 2018). "Thus, a potential mechanism of resistance to NAMPT inhibitors in NAPRT1-deficient cancer is NAPRT1 re-expression in the presence of co-administered NA." (PMID 25285661, 2014). "All these evidence support the targeting of NAMPT as a novel therapeutic strategy to enhance the efficacy of chemotherapeutic agents and targeted-therapy in tumors, as well as its potential diagnostic significance in cancer and its association with a poor survival rate." (PMID 36077374, 2022). "Indeed, NAMPT is implicated in driving pro-oncogenic and more aggressive phenotypes, and its overexpression has been associated with poor prognosis in different types of cancer." (PMID 34068917, 2021). "In particular, it appears that Sirt4 preserves NAD+ levels through nicotinamide phosphoribosyltransferase (NAMPT) activity, while loss of Sirt4 enhances glutamine metabolism, leading to genomic instability and oncogenic phenotype, thereby suggesting a protective role of this protein against cancer." (PMID 27379175, 2016). "Here, we demonstrate that diverse cancer cells that survive hypoxic or oxidative damage show rapid cell proliferation, and develop tolerance to damage associated with increased production of hydrogen sulfide (H2S) which drives up-regulation of nicotinamide phosphoribosyltransferase (Nampt)." (PMID 25248148, 2014). "Taken together, NAMPT plays a critical role in cancer by regulating tumor cell proliferation, migration, survival, and drug resistance, as well as influencing the immune status of the tumor microenvironment." (PMID 40775221, 2025). "Together, these results suggest that NAMPT inhibitors induce anti-tumor effects in NAMPT-dependent cancers by downregulating the production of NAD+, NADPH, and ATP, thereby affecting cholesterol, protein, and lipid synthesis." (PMID 40280967, 2025). "Strikingly, when examining genetic vulnerabilities of YAPoff cancers, two of the top-scoring hits are NAMPT and its partner protein in the NAD + salvage pathway, NMNAT1, matching the drug vulnerability data." (PMID 40440076, 2025). "Our findings reveal tumor-induced, NAMPT-dependent neutrophil reprogramming as a central driver of compromised antimicrobial defenses in cancer." (PMID 41387444, 2025). "These include antibody–drug conjugates (ADCs) that deliver NAMPT inhibitors specifically to cancer cells, as well as proteolysis-targeting chimera (PROTAC) technology NAMPT degraders that target both intracellular and extracellular forms of the enzyme." (PMID 40282553, 2025).